FAP (fibroblast activation protein alpha)
Diseases named in the same sentence as FAP in open-access papers (continued):
Sharing a sentence is not in itself a finding about the gene and the disease.
tumor (continued). "Importantly, although FAP has been implicated in regression of epithelial tumors mediated by Val-boroPro and other boronated dipeptides targeting extracellular enzymes, our data suggest that inhibition of intracellular DPPs may also contribute to tumor regression." (PMID 23554941, 2013). "Furthermore, FAP-specific re-directed T cells inhibited the growth of FAP positive human tumor cells in the peritoneal cavity of mice and significantly prolonged survival of mice." (PMID 23937772, 2013). "In addition, FAP-targeted vaccines reduced tumor collagen content and modulated the tumor immune microenvironment in preclinical models." (PMID 24349329, 2013). "Therefore, we evaluated the anti-tumor activity of FAP specific re-directed T cells by establishing an i.p. tumor model which constitutively expressed FAP as well as luciferase for in vivo detection of tumor cells." (PMID 23937772, 2013). "Interestingly, local treatment with the fusion protein against Fas+ cancer cells that had been transfected with FAP prevented tumor growth in the skin whereas un-transfected tumor cells were marginally inhibited." (PMID 23497165, 2013). "Indeed, proof of concept for restricted activation of 4-1BB-mediated co-stimulation was obtained for targeted delivery of 4-1BBL to the tumor stroma marker FAP using an scFvFAP-1BBL fusion protein." (PMID 23840967, 2013). "Targeting FAP with a humanized monoclonal antibody, sibrotuzumab, also showed no objective clinical responses; however, imaging studies revealed that the antibody preferentially localized to metastatic tumor sites after administration." (PMID 24349329, 2013). "We also report that the FAP+ matrix-induced tumor invasion phenotype is β1-integrin/FAK mediated." (PMID 21668992, 2011). "It was worth noting that of the 19 cases, especially in the region of the tumor-host interface where Calponin was negatively expressed, 19 (100%) cases showed FAP-a positive and 12 (63.16%) showed SMA positive, but 17 (89.47%) of these 19 cases reported negative for CD34 protein." (PMID 22067528, 2011). "FAP-α plays an important role in tumor growth and metastasis, as its expression on CAFs may create an environment permissive for cancer growth and invasion via collagenase and dipeptidyl peptidase activities." (PMID 22067528, 2011). "Further studies are needed to determine which cell type(s) express FAP and whether it serves a similar role of altering tumor stroma to promote invasion in GBM." (PMID 20646316, 2010). "Our results indicate that both malignant and benign tumours express FAP and DPP-IV." (PMID 19817894, 2009). "In addition, FAP expression in the primary tumor correlated with a worse 10-y overall survival rate in patients with RCC, suggesting a potential role of FAP PET imaging for detecting more aggressive tumors with a higher likelihood for metastatic spread and shorter survival." (PMID 41101974, 2026). "Enhancing tumor retention of FAP‐targeting agents could further improve their therapeutic efficacy." (PMID 40888104, 2026). "Furthermore, the chelates [177Lu]-PNT6555, PNT6952, and PNT6522 exhibited significant antitumor effects in FAP-positive tumor models, with [177Lu]-PNT6555 demonstrating the highest therapeutic efficacy, substantiating its potential as a promising candidate for radioligand therapy." (PMID 40918451, 2025). "Moreover, the vast number of oncologic entities for which FAPI may have applications exhibits heterogeneous uptake patterns, depending on the degree of FAP upregulation in the specific tumor entity." (PMID 40473461, 2025). "Interestingly, one FAP negative lymph node exhibited an increased FAP expression by the cancer cells themselves, while the tumor-associated stroma showed only minor FAPI uptake." (PMID 40272498, 2025). "We speculated whether FAP expression was affected by the fraction of B cells in the tumor." (PMID 41373408, 2025).
tumor (continued). "Furthermore, significant correlations emerged among FAP + CAFs, TILs, and CD68 + cells, and the co-occurrence of elevated FAP + CAFs, T-cytotoxic (CD8 +), T-regulatory (CD4 + FOXP3 +) cells, and macrophages (CD68 +) at the tumor center were independently associated with worse CSS." (PMID 39751643, 2025). "Therefore, this novel FAP-targeted radioactive tracer may be a promising tracer for non-invasive tumor imaging in subsequent clinical research, but its structure needs to be further modified to obtain better pharmacokinetic characteristics." (PMID 40006089, 2025). "With FAP beingmainly employed in nuclear medicine as a target for PET agents, furtherstrategies to consider may involve a different FAP-inhibitor targetingmoiety or a different FAP-targeting approach, such as a peptide toimprove the tumor-to-background ratio for fluorescence imaging applications." (PMID 39954291, 2025). "Additionally, patients may receive tailored regimens according to the different compositions of the tumor microenvironment, such as enrichment of FAP or collagen, enrichment of T cells or myeloid cells, or a poor immune cell profile." (PMID 40376004, 2025). "Furthermore, we present existing and new treatment methods that are centered on CAFs, such as suppression of the paracrine pathway (e.g., IL-6/STAT3, TGF-β), depletion of CAFs lineages by targeting fibroblast activation protein (FAP), and conversion toward tumor-restraining CAFs." (PMID 40959080, 2025). "In addition, high BGN expression was significantly associated with tumor invasion depth (p < 0.001), lymphatic vessel invasion (p = 0.001), and increased expression of CAF markers, αSMA (p = 0.003) and FAP (p = 0.022), and macrophage markers, CD68 (p = 0.049) and CD163 (p = 0.007), in ESCC tissues." (PMID 41465449, 2025). "Imaging with FAP inhibitor (FAPI) analogs may aid in characterizing the tumor microenvironment." (PMID 40430845, 2025). "Therefore, we speculate that the presence of these FAP+ cCAFs in the blood contributes to creating a tumor‐friendly microenvironment at the metastatic site." (PMID 38634185, 2025). "In the present study, we quantitatively evaluated FAP expression in surgically resected intrathoracic SFT tumor tissues, as we hypothesized that intrathoracic SFTs, which include SFTs of the pleura and pulmonary metastatic nodules derived from other organs, could be considered as diagnostic targets." (PMID 40126602, 2025). "Therefore, FAP is considered a promising target for both tumor imaging and therapy." (PMID 40006089, 2025). "Finally, since the present study focused on FAP-targeted diagnoses rather than therapeutic applications for SFTs, no specific investigation was conducted to determine whether FAP expression is localized within tumor cells or the tumor stroma." (PMID 40126602, 2025). "CAF-S1 also expresses high levels of FAP and is often located near epithelial tumor cells, forming a dense cellular “barrier”, and promoting the formation of an immunosuppressive microenvironment and distant tumor recurrence via high expression of molecules such as Cadherin 11 and CD73." (PMID 40890855, 2025). "Notably, FAP exhibits minimal expression in normal tissues but is highly abundant in the stroma of over 90% of malignant epithelial tumors, making it a promising target for both pan‐cancer therapy and tumor imaging." (PMID 40656546, 2025). "Furthermore, to clarify whether targeted CAF elimination was responsible for tumor inhibition by FAP/IL-15 CAR-T cells, we analyzed the expression of FAP and collagen type I in treated tumor tissues." (PMID 41455698, 2025). "Additionally, vaccination reduced the expression of FAPα and type I collagen in tumor tissue." (PMID 40918451, 2025). "Finally, FAP was associated with ECM and adhesion genes (FN1, COL5A1, SPOCK1, CDH13) and regulators of migration (NREP, SEMA5A), consolidating its central role in matrix deposition and tumor invasion, as previously shown." (PMID 41198614, 2025).
tumor (continued). "Moreover, FAP (fibroblast activation protein) inhibitors, such as Sibrotuzumab, target FAP expressed by stromal cells, aiming to disrupt the supportive role of these cells in tumor progression." (PMID 40979445, 2025). "There are three categories of tumors in the context of FAP imaging: desmoplastic tumors that have a high concentration of CAFs, tumors that do not have a significant desmoplastic reaction, and tumors where FAP is expressed on both the tumor stroma and the tumor cells." (PMID 39572227, 2025). "Therefore, similar to targeted removal of FAP positive tumor cells, targeted clearance of RA-FLS may become a promising option for treating RA." (PMID 40607439, 2025). "Due to the limited sample size, the evidence on the association between FAP/YAP and patient survival from our analysis of the TCGA cohort may be weakened after making the Bonferroni correction for additional variables such as sex and tumor location." (PMID 40959971, 2025). "Although the use of this intratumoral biomarker in clinical routine has not been protocolized, analyses of FAP in different solid tumors have shown that it has great potential as a prognostic marker, generally being significantly associated with tumor aggressiveness and inferior survival." (PMID 41373408, 2025). "The high uptake and tumor-to-background ratio of [68Ga]-Ga-FAPI might suggest that a beta-emitter FAP-based compound could potentially be an effective treatment strategy for tumors with high FAP expression." (PMID 39744055, 2025). "Similarly, FAP vaccination decreased tumor growth, suppressed metastasis, and increased survival." (PMID 40607439, 2025). "Thus, improving tumor affinity and retention while maintaining favorable pharmacokinetic profiles and minimizing off-target deposition is central to developing more effective FAP-targeted radiotheranostics." (PMID 41460404, 2025). "Fibroblast activation protein (FAP) IL2 variant (FAP-IL2v, also referred to as simlukafusp alfa or RO6874281) is a novel, monomeric, immune-cytokine designed to overcome the limitations of wild-type IL2 by selectively promoting immune responses in the tumor microenvironment." (PMID 39895413, 2025). "Additionally, inhibition of FAPα promotes the activation of T-lymphocytes and NK-cells, leading to increased production of key cytokines such as IL-2 and interferon-gamma (IFNγ), which strengthen the immune response against the tumor." (PMID 40918451, 2025). "In addition to chemotherapy and immunotherapy, radiotherapy sensitizers may also enhance the efficacy of FAP targeting for anti-tumor RLT." (PMID 40438601, 2025). "Furthermore, evidence indicates a correlation between FAP expression and tumor aggressiveness." (PMID 40272498, 2025). "We found that FAP may promote tumor progression via the “PI3K-Akt” signal pathway." (PMID 39055892, 2024). "Therefore, future attempts on the use of a pyridine-based FAP-targeted pharmacophore for the design of bispecific PSMA/FAP tracers need to include the optimization of linkers such as incorporating a piperazine-based linker to continue improving FAP-binding affinity and tumor uptake." (PMID 38398552, 2024). "Additionally, studies support the hypothesis that, once integrated into the plasma membrane, FAP concentrates within invadopodia (tumor cell protrusions)." (PMID 39765634, 2024). "Recent studies have shown that targeted FAP-positive CAFs may inhibit tumor growth." (PMID 38352864, 2024). "Furthermore, the presence of FAP-positive elongated stromal cells (iCAFs) in both week 4 and 8 BxPC-3 tumors, but predominantly in week 8 and 10 and negligible in week 4 Panc-1-fl tumors, indicates that FAP-expressing iCAFs mark an advanced tumor stage in the mouse models." (PMID 38891809, 2024). "FAP IHC is simple and inexpensive to use, so in the future it may be possible to stratify patients wo will benefit from FAP-diagnostics or FAP-treatment based on the IHC of the tumor biopsy." (PMID 38575990, 2024).
tumor (continued). "Given the lack of clinical and tumor features associated with FAP expression in this cohort, the absence of FAP expression in this case cannot be hypothesized." (PMID 39664608, 2024). "Thus, the model suggests a significant propensity for FAP expression at the tumor margins." (PMID 39519118, 2024). "Additionally, FAP expression doesn’t significantly correlate with tumor metastasis or staging." (PMID 39758423, 2024). "In summary, we reclassified the fibroblast subset and identified a FAP+ fibroblast subset as CAFs with an immune regulatory function in the PCa microenvironment, which could create an immunosuppressive microenvironment to promote tumor progression." (PMID 38483933, 2024). "Consequently, it is hypothesized that the Astatine (211At)-labeled FAP inhibitor (FAPI) selectively exerts anti-tumor effects through alpha-particle emission." (PMID 39519118, 2024). "Furthermore, overexpression of FAP has been reported to promote tumor microvascular formation, which suggests that it may be able to stimulate tumor angiogenesis." (PMID 38672409, 2024). "Furthermore, we found that Ga-AV02070, which has a carbonyl group at the para position to the pyridine nitrogen, has a better binding affinity to FAP and a higher tumor uptake compared to Ga-AV02053, which has a carbonyl group at the meta position to the pyridine nitrogen." (PMID 38398552, 2024). "Furthermore, the tumor retention of 177Lu-FAP-2286 exceeded that of 177Lu-FAPI-46." (PMID 38543239, 2024). "Thus, FAP-expressing CAFs are immunosuppressive and aid the growth of tumor." (PMID 38555315, 2024). "Also, FAP-expressing CAFs upregulate the expression of proinflammatory genes and may be responsible for tumor immune evasion in a mouse model of PDAC." (PMID 39030445, 2024). "We found that in HNSCC, FAP expression is significantly correlated with CTLA4, HAVCR2, and CD276, suggesting that FAP may play a key role in regulating immune evasion and tumor immune suppression, but further exploration is needed to elucidate the specific mechanisms." (PMID 38826849, 2024). "Despite the successful clinical outcomes of radiotracers targeting SSTR2 or FAP, single-receptor recognition may limit their sensitivity for disease detection, especially in early stages, due to tumor heterogeneity and relatively low receptor expression density." (PMID 39770488, 2024). "However, whether targeting SSTR or FAP, the blood clearance of these structures is rapid, which limits their absorption in the tumor, resulting in their therapeutic value being compromised by the short tumor residence time." (PMID 39770488, 2024). "Furthermore, combining anti-FAP CAR-T cell approaches with PD-1 inhibitors could offer a more effective strategy against tumor progression." (PMID 38693104, 2024). "Recently, we reported a new fibroblast activation (FAP) inhibitor radiopharmaceutical based on the 99mTc-((R)-1-((6-hydrazinylnicotinoyl)-D-alanyl) pyrrolidin-2-yl) boronic acid (99mTc HYNIC-D-Alanine-BoroPro)(99mTc-HYNIC-iFAP) structure for tumor microenvironment SPECT imaging." (PMID 38675193, 2024). "Therefore, reducing the infiltration of DAB2+ TAMs or SPP1+ TAMs at the tumor border and blocking their cellular communication with FAP+ CAFs may be another way to enhance anti-tumor immunity." (PMID 39239526, 2024). "Hence, FAP's interaction with these proteins not only amplifies its regulatory complexity but also accentuates its candidacy as a therapeutic target for disrupting these multifaceted tumor–stroma interactions." (PMID 38826849, 2024). "Notably, DAB2+ TAMs enriched in HCC, exhibiting significant spatial co-localization with FAP+ CAF in tumor border and may participate in shaping the TME." (PMID 39239526, 2024).
tumor (continued). "Recently, we reported a new fibroblast activation protein (FAP) inhibitor radiopharmaceutical based on the 99mTc-((R)-1-((6-hydrazinylnicotinoyl)-D-alanyl) pyrrolidin-2-yl) boronic acid (99mTc-HYNIC-D-Alanine-BoroPro)(99mTc-HYNIC-iFAP) structure for tumor microenvironment SPECT imaging." (PMID 38675193, 2024). "Hallmark pathway analysis confirmed that CTHRC1 and FAP myCAF cluster was most associated with pro-tumorigenic angiogenesis, EMT, hypoxia, and PI3K/AKT/mTOR signaling; and the myCAF (FAP, COL1A1,COL1A3) cluster may be critical for tumor growth and metastasis." (PMID 38525245, 2024). "Therefore, the inhibition of the FAP activity can impede tumor invasion." (PMID 39579201, 2024). "Nevertheless, the overexpression of FAP and thus the presence of large quantities of CAFs (20%–40% of total tumor mass) in 28 common tumors including breast, colorectal, pancreatic, and lung suggests that treatments targeting FAP may have broad applications for solid tumors." (PMID 39618102, 2024). "The specific targeting of FAP could contribute to targeting the tumor and the TME." (PMID 39335703, 2024). "Consequently, FAP represents a promising target and biomarker for anti‐tumor therapies." (PMID 40337455, 2024). "Notably, FAP-expressing CAFs contribute to immune evasion by promoting reactive oxygen species (ROS) generation and upregulating PD-L1 expression, further underscoring their role in tumor progression and therapeutic resistance." (PMID 39770505, 2024). "In other words, FAPα may be induced if the conditions are similar to those of the tumor tissue." (PMID 39596363, 2024). "Additionally, the tumor sections were also positive for murine FAPα." (PMID 39410013, 2024). "However, the biological processes underlying FAP expression in tumor progression and tumor immunity have not been fully elucidated." (PMID 37490719, 2023). "Mice vaccinated with recombinant adenoviral vectors containing FAP cDNA produced FAP-specific cytotoxic T lymphocytes capable of destroying FAP-expressing CAFs, suggesting FAP as a potential target for elimination of CAFs that may develop immunogenic tumor vaccines." (PMID 36672284, 2023). "Furthermore, eNVs-FAP–activated immune responses could initiate tumor ferroptosis by releasing interferon-gamma (IFN-γ) from CTLs and depleting FAP+ CAFs." (PMID 36922504, 2023). "This could be solved by the addition of an albumin binder to the pyridine-based FAP-targeted ligands to extend their blood residence time as similar approaches have been exploited to Increase the tumor uptake of radiolabeled quinoline-based FAPI-04 derivatives." (PMID 36986548, 2023). "Thus, our model mimics the properties of CAF in the tumor microenvironment and may serve as a simple model to allow for a broad screening of agents potentially affecting FAP expression." (PMID 37509656, 2023). "Therefore, FAP is considered a promising target for tumor imaging and therapy." (PMID 37321827, 2023). "In addition, FAP may express in non-tumor tissues such as wound healing sites, which makes it vital not to select a type of treatment that could affect the wound healing process." (PMID 37316886, 2023). "In addition, FAP as a target can achieve the effective inhibition of tumor growth." (PMID 36838669, 2023). "Several studies have shown that depletion of FAP-expressing stromal cells overcomes immunosuppression in non-immunodeficient normal mice, eliciting the immune system and a number of cytokines that promote rapid tumor and stromal cell death and allow for immune control of growth." (PMID 38706713, 2023). "In addition, targeting FAP imaging may break new ground with its applications, such as non-invasive tumor characterization, tumor staging and tumor treatment effect monitoring." (PMID 36675506, 2023). "In addition, we found that FAP+ CAF bound to CD63 in tumor cells by secreting the TIMP1 ligand." (PMID 37333982, 2023).